SIRT1 (sirtuin 1)
Diseases named in the same sentence as SIRT1 in open-access papers (continued):
Sharing a sentence is not in itself a finding about the gene and the disease.
Shock (7 papers, 2015 to 2022). The state in which profound and widespread reduction of effective tissue perfusion leads first to reversible, and then if prolonged, to irreversible cellular injury. "The SIRT1-activating compounds upregulate SIRT1 expression to reduce cisplatin- or hemorrhagic-shock-induced AKI, directly impacting catalase expression, eliminating free radicals, and promoting ATP generation." (PMID 35277012, 2022). "In this study, we evaluated SIRT1-PGC-1α axis activity in small intestine tissue subjected to severe hemorrhagic shock and found a downstream target of this pathway." (PMID 26301045, 2015). "Similarly, in a rat model of acute hemorrhagic shock, PD has been demonstrated to prevent the decreases in SIRT1 expression and activity." (PMID 33101591, 2020). "In addition, it has been suggested polydatin increased SIRT1 activity leading to attenuation of mitochondrial damage in hemorrhagic shock." (PMID 33308195, 2020). "In addition, anti-inflammatory effect of IFN-β through SIRT1 upregulation and down regulation of inflammatory cytokines including IL-6 has been investigated in lethal endotoxic and septic shock." (PMID 29423066, 2018). "First, we confirmed that SIRT1 protein level and activity were decreased in the setting of intestinal injury after severe hemorrhagic shock and reperfusion, and these changes may be related to alterations in the SIRT1-PGC-1α-SOD2 axis signaling pathway." (PMID 26301045, 2015).
spinal cord injury (7 papers, 2018 to 2025). Penetrating and non-penetrating injuries to the spinal cord resulting from traumatic external forces (e.g., WOUNDS, GUNSHOT; WHIPLASH INJURIES; etc.). "Although the direct effect of SIRT1 on axonal regeneration remains obscure, activation of SIRT1 has been shown to exert beneficial effects on motor function in the animal model of spinal cord injury (SCI)." (PMID 30416425, 2018). "It has also been reported that SIRT1 promotes astroglial differentiation to facilitate astrogliosis and healing, which results in scarring at the damaged site, commonly observed in brain and spinal cord injuries." (PMID 40426868, 2025). "Sirtuin 1 (Sirt1), a key NAD+‐dependent deacetylase, has become a leading therapeutic target for spinal cord injury (SCI) repair due to its regulation of multiple pathological processes, including inflammation, oxidative stress, and cell death." (PMID 39915897, 2025).
acute coronary syndrome (6 papers, 2016 to 2025). Signs and symptoms related to acute ischemia of the myocardium secondary to coronary artery disease. "Ultimately, the polymorphism rs3758391 T>C located in the gene promoter is associated with a higher expression of SIRT1 mRNA during acute coronary syndromes." (PMID 34690807, 2021). "Notably, rs3758391 T→C, located in the SIRT1 gene promoter, is associated with elevated SIRT1 mRNA levels in patients with acute coronary syndromes." (PMID 37894840, 2023). "The pathophysiology of acute coronary syndromes differs from the pathophysiology of chronic coronary syndromes, thus explaining the differential behavior of SIRT1 in patients with NSTEMI and those with APS." (PMID 40507709, 2025). "Consistently, a reduced intracellular expression of SIRT1 gene was observed in patients with stable coronary artery disease (sCAD) and acute coronary syndrome, whereas increased circulating levels were associated with sCAD." (PMID 34690807, 2021). "Our working hypothesis was that levels of sC5b-9, RGC-32, and SIRT1 differ according to with plaque instability among acute coronary syndromes, chronic coronary syndromes, and control patients." (PMID 40507709, 2025). "For example, the increased expression of visfatin in acute coronary syndrome patients might exert a protective effect by the upregulation of the NAMPT/NAD+/Sirt1 signaling pathway." (PMID 36128447, 2022). "Finally, plasma levels of SIRT1 and PCSK9 were assessed at baseline in patients with acute coronary syndromes." (PMID 40653676, 2025).
allergic disease (6 papers, 2017 to 2024). An immune response that occurs following re-exposure to an innocuous antigen, and that requires the presence of existing antibodies against that antigen. "Sirt1, a key regulator of metabolism and longevity, has recently been implicated in the regulation of allergic reactions, although the underlying mechanism remains unclear." (PMID 28744004, 2017). "SIRT1 was shown to inhibit Th9 cell differentiation in vitro and mice harboring a T cell-specific deletion of SIRT1 exhibited exacerbated airway inflammation in an OVA-induced allergy model." (PMID 29599783, 2018). "Overall, our results provide a molecular explanation for the beneficial role of Sirt1 in allergy and underscore a potential application of Sirt1 activators as a new class of anti-allergic agents." (PMID 28744004, 2017). "SIRT1 has been reported to be involved in several physiological or pathological processes such as aging, inflammation, immune responses, oxidative stress and allergic diseases." (PMID 39081309, 2024). "Similarly, in the allergic diseases group, the SIRT1 concentration in the case group was 0.95 ng/mL higher than that in the control group (WMD, 0.95 ng/mL; 95% CI 0.43, 1.47 ng/mL; P< 0.001; I2 = 87.9%)." (PMID 39676853, 2024). "In recent years, the potential roles of SIRT1 in allergic diseases has been confirmed." (PMID 39081309, 2024). "In this context, a strategy that activates Sirt1 may have a novel therapeutic potential to treat allergic diseases." (PMID 28744004, 2017). "However, the roles of Sirt1 in allergic diseases are controversial, because Sirt1 reportedly prevents or exacerbates allergic responses in distinct settings." (PMID 28744004, 2017). "Furthermore, we highlight the therapeutic effects of targeting SIRT1 in allergic diseases." (PMID 39081309, 2024). "Inhibition of miR‐138‐5p in hMSCs enhanced its effects in attenuating inflammatory responses and allergic reaction in the ARAS model, which is presumably regulated by SIRT1 and the HMGB1/TLR4 pathway." (PMID 33973707, 2021). "However, the roles of Sirt1in allergy have not been firmly established, since it is uncertain whether resveratrol acts on only Sirt1 or some another unknown molecule(s) to exert its actions." (PMID 28744004, 2017).
anorexia nervosa (6 papers, 2020 to 2025). A disorder most often seen in adolescent females characterized by a refusal to maintain a minimally normal body weight, an intense fear of gaining weight, a disturbance in body image, and, in postmenarcheal females, the development of amenorrhea. "Several reports have shown that serum SIRT1 levels correlated negatively with BMI and were elevated in patients with anorexia nervosa." (PMID 38529393, 2024). "The aim of this study was to assess whether circulating SIRT1 varies consistently with leptin, ghrelin, body mass index (BMI), and IgG reactive to hypothalamic antigens in anorexia nervosa (AN)." (PMID 37373917, 2023). "SIRT1 activation by resveratrol reduced BMA and promoted osteogenesis in an anorexia nervosa model by modulating the acetylation levels of Runx2 and FoxO1." (PMID 40243497, 2025).
autism (6 papers, 2018 to 2026). Persistent deficits in social interaction and communication and interaction as well as a markedly restricted repertoire of activity and interest as well as repetitive patterns of behavior. "Recent reports suggest that there is a close relationship between SIRT1 levels in the cerebral tissues and the pathogenic events that occur in autism." (PMID 39596986, 2024). "We did suggest the neuroprotective effect for AFE against VPA-induced autism might involve upregulation of Sirt-1 protein." (PMID 36826050, 2023). "In our studies, while the NSC growth rate was higher in patients with autism, SIRT1 was not affected in NSCs, though it was severely reduced in the astrocytes of patients with autism." (PMID 38994948, 2024). "Moreover, the astrocytes of patients with autism exhibited higher expression of TGFB1 and TGFB2 but reduced expression of proliferator genes such as CXCR4 and NURR1 in addition to RELN, EN2, HAP1, SIRT1, and GPX1 vs. controls." (PMID 38994948, 2024).
B-cell lymphoma (6 papers, 2014 to 2025). "In rare B-cell lymphomas, such as primary effusion lymphoma, SIRT1 has been shown to be necessary for the proliferation and maintenance of tumor cells, while SIRT1 inhibitors, such as Tenovim-6, efficiently decrease the neoplastic growth process." (PMID 36230534, 2022). "Additionally, an important functional relationship between SIRT1 and HSP90 has been observed in B-cell lymphoma (DLBCL) cells, where SIRT1 inhibition reduced heat-stress-induced HSP90 induction." (PMID 40757581, 2025). "In particular, compounds 55 (IC50 SIRT2 0.25 μM and <25% inhibition at 50 μM against SIRT1 and SIRT3) and 56 (IC50 SIRT2 0.78 μM and <25% inhibition at 50 μM against SIRT1 and SIRT3) showed apoptotic as well as strong anti-proliferative properties against B-cell lymphoma cells." (PMID 31973227, 2020). "We previously reported a dual SIRT1/2 inhibitor called cambinol 1 (in vitro IC50 54 and 46 μM respectively) that sensitized cells to paclitaxel and etoposide and, was cytotoxic as a single agent against B-cell lymphoma cell lines in vitro and xenograft models in vivo." (PMID 31973227, 2020).
calcification (6 papers, 2020 to 2025). Process by which organic tissue becomes hardened by the physiologic deposit of calcium salts. "Mechanistically, the antiaging factor SIRT1 mediated the inhibitory effects of IMD on aging-associated vascular calcification, while in renal failure-related vascular calcification, the protective role of IMD was mainly mediated by another antiaging factor, α-klotho." (PMID 36225176, 2022). "SIRT1 also has protective effects against vascular calcification and therefore could be developed as a therapy for both CKD and CKD complications." (PMID 35795148, 2022). "Based on these findings, we postulate that resveratrol and estrogen via SIRT1 activation may play a key role in modulating OPG/RANKL signaling in aortic calcification." (PMID 34563044, 2021). "Notably, SIRT1, SIRT2, SIRT3, SIRT6, and SIRT7 have demonstrated therapeutic potential in the treatment of vascular calcification." (PMID 41480421, 2025). "Activation of both SIRT1 and SIRT6 may become a promising clue for treatment of vascular calcification." (PMID 41353172, 2025). "When the expression of SIRT1 is decreased, the inhibitory effect of Spd on vascular smooth muscle cell calcification is also abolished, suggesting that SIRT mediates the protective effect of Spd on the progression of vascular calcification." (PMID 35795148, 2022).
carotid atherosclerosis (6 papers, 2014 to 2023). A thickening and loss of elasticity of the walls of carotid arteries that occur with formation of atherosclerotic plaques. "Recently, it was found to inhibit the inflammatory response of carotid atherosclerosis induced by a high-fat diabetic diet in rats by regulating the AMPK/SIRT1/NF-κB pathway, and also reduced inflammation in obese mice via the AMPKα1/SIRT1 pathway." (PMID 37959807, 2023). "We suggest that ferroptosis of cells increases the expression of the IL-1B gene by inhibiting GPX4 and SIRT1, which activates the inflammatory response, produces a large amount of ROS, and finally leads to the occurrence of carotid atherosclerosis." (PMID 36393970, 2022). "Our study is the first to report a significant association of genetic polymorphisms at SIRT1 and FOXO1 with a carotid atherosclerosis." (PMID 25273948, 2014). "The pathophysiological functions of SIRT1 and FOXO1 in vascular homeostasis and carotid atherosclerosis have been described within the last years and exert protective roles in case of SIRT1 and controversial roles for FOXO1." (PMID 25273948, 2014). "This study demonstrated associations of genetic variations at the SIRT1 and FOXO1 loci with carotid atherosclerosis and highlighted the need for further investigation by functional studies." (PMID 25273948, 2014). "This may hold promise as a novel therapeutic approach for carotid atherosclerosis since the SIRT1/AMPK pathway is key to a number of vasculoprotective processes." (PMID 28659610, 2017). "Therefore, further replication studies and also functional studies are warranted to elucidate the molecular mechanism of this association and the role of these genetic variations at SIRT1 and FOXO1 in carotid atherosclerosis." (PMID 25273948, 2014). "However, the functional consequences of SIRT1 and FOXO1 genetics in regulation of carotid atherosclerosis remain incompletely understood and should be investigated in further functional studies." (PMID 25273948, 2014). "Association of genetic polymorphisms at the SIRT1 and FOXO1 loci with carotid atherosclerosis have not been reported before." (PMID 25273948, 2014). "It is not known, if genetic polymorphisms (SNPs) at the SIRT1 and FOXO1 have an influence on carotid atherosclerosis." (PMID 25273948, 2014).
Chagas disease (6 papers, 2016 to 2023). A parasitic infection caused by Trypanosoma cruzi. "In this review, we discuss the molecular mechanisms by which SIRT1 can potentially improve mitochondrial function and control oxidative and inflammatory stress in Chagas disease." (PMID 34178728, 2021). "In this review, we discuss various roles of SIRT1 with a focus on its beneficial effects in regulating Chagas disease pathogenesis." (PMID 34178728, 2021). "In Chagas disease, for example, resveratrol in mice was effective in reversing functional heart disease, and heart function was improved by sirtuin 1 (SIRT-1) targeted therapy for Trypanosoma cruzi infection." (PMID 32244373, 2020). "In this study, we determined the progenitor lineage of Mo/Mφ contributing to inflammation and examined the regulatory role of SIRT1 in modulating the Mo/Mφ response in Chagas disease." (PMID 31905606, 2019). "We next determined if SIRT1 agonists controlled the chronic oxidative and inflammatory stresses that are hallmarks of Chagas disease." (PMID 27764247, 2016). "We first determined if enhancing the SIRT1 activity would preserve the cardiac function in Chagas disease." (PMID 27764247, 2016). "In this study, we aimed to determine whether treatment with SIRT1 agonists will be beneficial in improving the heart function in Chagas disease." (PMID 27764247, 2016). "Co-delivery of SIRT1 agonists with other small molecules that inhibit mitochondrial dysfunction, cardiac fibrosis, and parasite persistence will potentially form a complete therapeutic regimen against Chagas disease." (PMID 27764247, 2016). "In this study, we determined whether enhancing the activity of sirtuin 1 (SIRT1) would be beneficial in maintaining heart health in Chagas disease." (PMID 27764247, 2016). "Together, these results suggested that SIRT1-FAK regulate the downstream transcription factors involved in Mφ maturation, survival, and activation during Chagas disease." (PMID 31905606, 2019). "We also found that proinflammatory macrophages can be reprogrammed to healing phenotype through enhancing the SIRT1 activity that inhibits the FAK signaling of factors involved in macrophage proliferation and proinflammatory activation in Chagas disease." (PMID 31905606, 2019). "Whether PARP1–SIRT1 imbalance occurs in human Chagas disease and whether PARP1 inhibitors or SIRT1 agonists will be useful in improving the cardiac outcomes in human Chagas disease remain to be investigated in future studies." (PMID 34178728, 2021). "We conclude that Tc inhibition of SIRT1/PGC1α activity was not a key mechanism in mitochondrial biogenesis defects during Chagas disease." (PMID 27764247, 2016). "We found that treatment with SIRT1 agonists, given in a therapeutic window of time after Trypanosoma cruzi infection, had no beneficial effects in reducing the cardiac remodeling and mitochondrial biogenic defects in chagasic mice." (PMID 27764247, 2016). "The decline in SIRT1/PGC1α activity was not the key mechanism in mitochondrial biogenic defects in Chagas disease, and therefore SIRT1-targeted therapy did not normalize the PGC1α/NRF1-dependent mitochondrial biogenesis and cardiac remodeling in chagasic disease." (PMID 27764247, 2016). "Likewise, how the crosstalk or substrate allocation between SIRT1 and PARP1 is regulated is not known, and further studies will be needed to understand their precise role in human health and disease, especially as related to Chagas disease." (PMID 34178728, 2021).
chronic prostatitis (6 papers, 2011 to 2025). An infectious or non-infectious chronic inflammatory process that affects the prostate gland. "As an oncogene, SIRT1 is over-expressed in the malignant tumors of prostate, breast, pancreas, and liver." (PMID 25826085, 2015). "Our team previously demonstrated that alcohol exacerbated the progression of chronic prostatitis via upregulating the NLRP3 inflammasome 13, and melatonin could alleviate chronic prostatitis development via the SIRT1/NLRP3 pathway." (PMID 38993566, 2024). "Resveratrol activates Sirt1 to downregulate c-kit/SCF, thereby mitigating the progression of chronic prostatitis." (PMID 40918147, 2025).
dilated cardiomyopathy (6 papers, 2012 to 2023). Cardiomyopathy which is characterized by dilation and contractile dysfunction of the left and right ventricles. "Concerning myocardial homeostasis, in vivo observations have shown that Sirt1 is downregulated in failing hearts, and its loss of function by gene deletion leads to the development of a dilated cardiomyopathy phenotype." (PMID 37957697, 2023). "The deletion of Sirt1 in mice causes the development of dilated cardiomyopathy, and subsequently being more vulnerable to cardiac injury induced by ischemia/reperfusion (I/R)." (PMID 33324687, 2020). "Overexpression of SIRT1 at a high level (20-fold) or SIRT1-deficiency caused dilated cardiomyopathy." (PMID 26389889, 2015). "On the other hand, SIRT1-deficient mice also showed a progressive dilated cardiomyopathy strongly associated with mitochondrial dysfunction, and SIRT1 plays an essential role in the maintenance of mitochondrial integrity and modulates the Mef2 transcription factors in the heart." (PMID 26389889, 2015).
fibrosarcoma (6 papers, 2010 to 2022). A malignant mesenchymal fibroblastic neoplasm affecting the soft tissue and bone. "In line with our findings, reduced SIRT1 expression under hypoxia was previously demonstrated in renal and fibrosarcoma cells." (PMID 32796661, 2020). "Similarly, endogenous SIRT1-ΔExon8 protein also migrated at 300 kDa in murine fibrosarcoma cells." (PMID 20975832, 2010). "In addition, miR-373 was also found toup-regulate MMP-9 by regulating SIRT1, leading to activation of the RAS/RAF/MEK/ERK pathways in fibrosarcoma cells." (PMID 34096221, 2021). "A previous study on fibrosarcoma cells showed an increase in MMP9 activity could be explained by miR-520c and miR-373 that acts by targeting the 3’UTR of mTOR and SIRT1 and its downstream effectors and kinases to inactivating signaling pathways that negatively regulate MMP9 expression." (PMID 25774514, 2015).
Impaired glucose tolerance (6 papers, 2011 to 2022). An abnormal resistance to glucose, i.e., a reduction in the ability to maintain glucose levels in the blood stream within normal limits following oral or intravenous administration of glucose. "SIRT1−/− animals exhibited increased fat mass, impaired glucose tolerance, and attenuated insulin sensitivity." (PMID 35721807, 2022).